PRDM13 (PR/SET domain 13)
Description:
May be involved in transcriptional regulation. Is required for the differentiation of KISS1-expressing neurons in the arcuate (Arc) nucleus of the hypothalamus. Is a critical regulator of GABAergic cell fate in the cerebellum, required for normal postnatal cerebellar development (By similarity).
Synonyms: PFM10; CDIDHH; MU-MB-20.220; PCH17
Tractability: No criterion of Open Targets' tractability assessment is met for any kind of drug.
Target class: Enzyme; Transferase
Gene: Protein-coding gene on chromosome 6 (99,606,774 to 99,615,578, forward strand). Ensembl gene ENSG00000112238.
Subcellular location: Nucleus
Subcellular location (Human Protein Atlas): Nuclear speckles; Nucleoplasm; Cytosol
Gene Ontology:
Molecular function: histone methyltransferase activity; chromatin binding; RNA polymerase II-specific DNA-binding transcription factor binding
Biological process: regulation of gene expression; chromatin remodeling; GABAergic neuron differentiation; hypothalamus cell differentiation
Cellular component: nucleus
Genetic constraint (gnomAD): Loss-of-function variants: 15 observed, 33.3 expected, observed/expected ratio (o/e) 0.45, 90% interval 0.3 to 0.69. The synonymous counts are far from expectation, so gnomAD's model fits this gene poorly and the ratio says little. Missense variants: 1,044 observed, 938.01 expected, observed/expected ratio (o/e) 1.11, 90% interval 1.06 to 1.17. Synonymous variants: 531 observed, 438.37 expected, observed/expected ratio (o/e) 1.21, 90% interval 1.13 to 1.3.
Homologues: Orthologues: chimpanzee PRDM13 (99% identical), macaque PRDM13 (98% identical), rabbit PRDM13 (91% identical), pig PRDM13 (89% identical), dog PRDM13 (85% identical), mouse Prdm13 (83% identical), rat Prdm13 (78% identical), tropical clawed frog prdm13 (57% identical), zebrafish prdm13 (54% identical), Drosophila melanogaster Prdm13 (19% identical). Paralogues in human: ZBTB49 (13% identical), ZBTB21 (12% identical), BCL6B (12% identical), BCL6 (11% identical), ZBTB46 (11% identical), ZBTB14 (11% identical), FEZF1 (10% identical), FEZF2 (10% identical), ZBTB7B (10% identical), ZNF280D (10% identical), GFI1 (9% identical), ZBTB12 (9% identical), and 16 more.
Diseases named in the same sentence as PRDM13 in open-access papers:
PRDM13 is named in the same sentence as 33 diseases in open-access papers, as found by Europe PMC text mining. Sharing a sentence is not in itself a finding about the gene and the disease. The quoted sentences say what the papers report.
North Carolina macular dystrophy (4 papers, 2017 to 2025). North Carolina macular dystrophy (NCMD) is a non-progressive autosomal dominant macular disorder of congenital or infantile onset characterized by loss of central vision, the accumulation of drusen in the macula and atrophy of photoreceptor cells with a variable phenotype at macular examination. "North Carolina Macular Dystrophy (NCMD), a rare autosomal dominant disorder, arises from noncoding single nucleotide variants (SNVs) near PRDM13 or duplications overlapping DNase I hypersensitive sites (near PRDM13/IRX1)." (PMID 41210874, 2025).
hypogonadotropic hypogonadism (3 papers, 2021 to 2024). Abnormal ovarian or testicular function due to insufficient hormonal stimulation from the hypothalamic-pituitary axis. "In this regard, it is interesting that a most recent study has reported that a recessive mutation to the human PRDM13 gene causes ataxia with cerebellar hypoplasia and delayed puberty with hypogonadotropic hypogonadism." (PMID 37045472, 2023).
Macular dystrophy (3 papers, 2017 to 2025). Macular dystrophy is a nonspecific term for retinal degeneration, generally confined to the macula, usually presumed of genetic origin. "Notable exceptions relevant to IRD include variants in the non‐coding region upstream to PRDM13 associated with North Carolina Macular Dystrophy (OMIM 13650) and CEP290:c.2991+1655A>G, a prevalent cause of LCA in European patients." (PMID 33749171, 2021).
Cerebellar hypoplasia (2 papers, 2021 to 2024). Cerebellar hypoplasia is a descriptive term implying a cerebellum with a reduced volume, but a normal shape and is stable over time. "To understand how PRDM13 deficiency can lead to cerebellar hypoplasia, we first examined PRDM13 expression during development." (PMID 34730112, 2021). "The combination of developmental delay, CHH, cerebellar hypoplasia, scoliosis, and intellectual disability associated with PRDM13 mutation differs significantly from what is seen in other conditions with CHH and cerebellar atrophy, such as Gordon Holmes syndrome (GHS)." (PMID 34730112, 2021). "Supporting this hypothesis, it has been reported that a different form of cerebellar hypoplasia (PCH17), caused by bi-allelic variants in PRDM13 (OMIM *6167441 and #619909), comes with early disruption of cerebellar and brain stem development." (PMID 39034883, 2024).
Intellectual disability (2 papers, 2021 to 2024). "Here, we report a recessive syndrome associated with a PRDM13 mutation in unrelated patients exhibiting intellectual disability, ataxia with cerebellar hypoplasia, scoliosis, and delayed puberty with CHH." (PMID 34730112, 2021). "Patients with SOX11 syndrome have intellectual disability, patients with loss-of-function variants in NLGN3 have developmental delay and autistic spectrum disorders, and those with cerebellar hypoplasia and intellectual disability are associated with recessive variants in the PRDM13 gene." (PMID 38436980, 2024).
Alzheimer disease (1 paper, 2020). A progressive, neurodegenerative disease characterized by loss of function and death of nerve cells in several areas of the brain leading to loss of cognitive function such as memory and language. "Seven out of 18 genes are associated with neurological diseases: Alzheimer’s disease (CPT1A, SUFU, ZSWIM8, PDCD4), schizophrenia (HTT, NBEAL2) and Parkinson disease (PRDM13)." (PMID 32599769, 2020). "Interestingly, there were seven genes associated with neurological disorders, including Alzheimer’s disease (CPT1A, SUFU, ZSWIM8, PDCD4), schizophrenia (HTT, NBEAL2) and Parkinson’s disease (PRDM13)." (PMID 32599769, 2020).
brain tumors (1 paper, 2025). "PRDM13, a neuron-specific PR/SET protein, regulates GABAergic vs. glutamatergic fate during cerebellar development and is frequently silenced by promoter methylation in embryonal brain tumors." (PMID 41228218, 2025).
Cerebellar atrophy (1 paper, 2021). Cerebellar atrophy is defined as a cerebellum with initially normal structures, in a posterior fossa with normal size, which displays enlarged fissures (interfolial spaces) in comparison to the foliae secondary to loss of tissue. "In contrast with the late-onset neurodegenerative etiology of cerebellar atrophy in these conditions, we show here that PRDM13 mutations disrupt cerebellar development." (PMID 34730112, 2021).
glioma (1 paper, 2023). A benign or malignant brain and spinal cord tumor that arises from glial cells (astrocytes, oligodendrocytes, ependymal cells). "Overexpression of PRDM13 in U87 glioma cells significantly inhibits cell migration and invasion by interacting with deleted liver cancer 1 (DLC1) and ARHGAP30 (Rho GTPase-activating protein 30) genes." (PMID 36982660, 2023).
Gonadotropin deficiency (1 paper, 2021). A reduced ability to secrete gonadotropins, which are protein hormones secreted by gonadotrope cells of the anterior pituitary gland, including the hormones follitropin (FSH) and luteinizing hormone (LH). "As patients carrying homozygous mutations of PRDM13 display gonadotropin deficiency, we first analyzed the GnRH neuron system in Prdm13–/– mutants." (PMID 34730112, 2021).
Leber congenital amaurosis (1 paper, 2025). Leber congenital amaurosis (LCA) is a retinal dystrophy defined by blindness and responses to electrophysiological stimulation (Ganzfeld electroretinogram (ERG)) below threshold, associated with severe visual impairment within the first year of life. "To further investigate the DEGs found within the neural retina samples, we compiled a list of genes associated with Leber congenital amaurosis, macular degeneration and RP22 and found that genes linked to these diseases were repressed in the PRDM13-OE retinas compared with controls." (PMID 40824246, 2025).
macular coloboma (1 paper, 2022). "Heterozygous, noncoding variations upstream of the PRDM13 gene were reported to be associated with NCMD; therefore, the affected individual also underwent a Sanger sequence to elucidate the relevant remote variants as the cause of macular coloboma." (PMID 36429029, 2022).
progressive bifocal chorioretinal atrophy (1 paper, 2021). Progressive bifocal chorioretinal atrophy (PBCRA) is an early-onset chorioretinal dystrophy characterized by large atrophic macular and nasal retinal lesions, nystagmus, myopia, poor vision, and slow disease progression. "Intriguingly, changes near PRDM13 that have been associated with NCMD have also been implicated in a different condition, progressive bifocal chorioretinal atrophy (PBCRA)." (PMID 34125159, 2021).
retinal degeneration (1 paper, 2025). Degeneration of the retina. "Of note, some of these amacrine cell-related genes significantly altered by elevated PRDM13 have also been shown to be associated with cone photoreceptors, retinal degeneration, and patterning in retinal development." (PMID 40824246, 2025). "PRDM13-OE and wildtype littermates were provided dox for 10 days, and eyes underwent immunostaining for key retinal cell type markers after the time in which retinal degeneration no longer progresses, either 3 weeks after the removal of dox or 11 weeks after the removal of dox." (PMID 40824246, 2025).
retinal disease (1 paper, 2025). "To investigate mechanisms regulating photoreceptor health, we developed a mammalian model to induce controlled expression of a transcriptional regulator that has been linked to retinal development and retinal disease: PRDM13." (PMID 40824246, 2025).
retinal dystrophies (1 paper, 2025). "We also discovered that genes associated with inherited retinal dystrophies were downregulated in the retina when PRDM13 expression was elevated." (PMID 40824246, 2025). "Dysregulated PRDM13 has been linked to retinal dystrophy, indicating a role for PRDM13 in the retina." (PMID 40824246, 2025). "Markedly, we found that PRDM13 expression downregulated the photoreceptor marker Prdm1 as well as Nr2e3—a key regulator of photoreceptor specification also implicated in retinal dystrophies—and affected NR2E3’s direct and indirect targets." (PMID 40824246, 2025).
cancer (9 papers, 2009 to 2024). A tumor composed of atypical neoplastic, often pleomorphic cells that invade other tissues. "While both PRDM10 and PRDM13 have been implicated in key developmental processes, such as cell fate specification, and in various cancer, they remain significantly less well-characterized compared to their counterparts in the PRDM family." (PMID 33809237, 2021). "PRDM10 and PRDM13 have been implicated in both vertebrate development and cancer, but their expression profiles and function are less well-characterized relative to other members of the PRDM family." (PMID 33809237, 2021). "Most of the DMH-Prdm13-KO and control mice died by malignant neoplasm (83% and 86%, respectively), revealing that deletion of Prdm13 in the DMH does not directly affect age-associated malignancy." (PMID 37045472, 2023). "Despite the pleiotropic roles of PRDM10 and PRDM13 in both development and pathological states such as cancer, little is known about their expression profiles." (PMID 33809237, 2021). "Specifically, PRDM12 and PRDM13 were largely overexpressed in many cancers whereas PRDM16 and ZFPM2/FOG2 were often downregulated." (PMID 30347759, 2018). "PRDM9 and PRDM13 also showed exclusive expression in cancer, but their biological roles in these tumors are unclear." (PMID 26110843, 2015). "Because malignant neoplasm is the main cause of death in C57BL/6J mice, we next tested whether Prdm13 deficiency in the DMH affects the incidence of malignant neoplasm." (PMID 37045472, 2023). "Consistent with the overexpression of PRDM10 and PRDM13 in numerous cancer types, both proteins were expressed in a wide spectrum of tissues in the developing embryo, supporting the need for future studies to probe their functional roles beyond what has been previously reported in the literature." (PMID 33809237, 2021). "Interestingly, in our pan-cancer reanalysis of the RNA-sequencing datasets from TCGA, we observed a high overexpression of PRDM13 in many cancer types; these included carcinomas from head and neck, bladder, kidney, lung, cervical, and colorectal tissues." (PMID 32290321, 2020). "However, pan-cancer reanalysis has shown high PRDM13 overexpression in many cancers." (PMID 36982660, 2023).
tumor (2 papers, 2018 to 2020). "PRDM13 was reported for the first time as a tumor suppressor in medulloblastoma, in a study aimed at identifying novel tumor markers and targets for brain tumor immunotherapy through the isolation of tumor antigens by the SEREX (serological analysis of cDNA expression libraries) approach." (PMID 32290321, 2020). "Of note, TCGA gene expression profiling of PRDM genes revealed significant overexpression of PRDM12 and PRDM13 in many tumor types whereas ZFPM2/FOG2, PRDM8, and PRDM16 were more often downregulated in tumor tissues." (PMID 30347759, 2018).
neurodegenerative disease (1 paper, 2021). A disorder of the central nervous system characterized by gradual and progressive loss of neural tissue and neurologic function. "Prdm13–/– mice did not exhibit any signs suggestive of a neurodegenerative disease associated with aging (age range, 8–12 months, n = 9)." (PMID 34730112, 2021).
PRDM13 also shares sentences with these, for which no sentence is quoted: amyotrophic lateral sclerosis (1 paper); Ataxia (1); breast carcinoma (1); developmental delay (1); Gordon Holmes syndrome (1); hypogonadism (1); macular degeneration (1); malignant glioma (1); microcephaly (1); neurological diseases (1); Obesity (1); Parkinson disease (1); schizophrenia (1); scoliosis (1).